COL26A1 (collagen type XXVI alpha 1 chain)
Synonyms: Emu2; EMID2; EMI6; SH2B
Tractability: Antibody: its Gene Ontology location is reachable by antibodies, with high confidence; UniProt places it where antibodies can reach, with medium confidence; UniProt predicts a signal peptide or a membrane-spanning region. PROTAC: its protein half-life has been measured.
Safety:
Unwanted effects reported when the protein is acted on. In parentheses: how it was acted on, where the effect was seen, and who reports it.
asthma (source: ClinPGx)
hearing and vision-related side-effects (source: ClinPGx)
Gene: Protein-coding gene on chromosome 7 (101,362,407 to 101,559,029, forward strand). Ensembl gene ENSG00000160963.
Subcellular location: Secreted, extracellular space, extracellular matrix
Subcellular location (Human Protein Atlas): Vesicles; Predicted to be secreted
Pathways (Reactome):
Extracellular matrix organization: Collagen biosynthesis and modifying enzymes; Collagen chain trimerization; Collagen degradation
Gene Ontology:
Cellular component: extracellular matrix; collagen type XXVI trimer; endoplasmic reticulum lumen; extracellular region; plasma membrane; endoplasmic reticulum; Golgi apparatus
Genetic constraint (gnomAD): Loss-of-function variants: 36 observed, 41.53 expected, observed/expected ratio (o/e) 0.87, 90% interval 0.66 to 1.14. The upper end of that interval is the gene's LOEUF score, 1.14, which puts it in group 5 of 6, group 1 being the genes least tolerant of losing a copy. Missense variants: 573 observed, 512.75 expected, observed/expected ratio (o/e) 1.12, 90% interval 1.04 to 1.2. Synonymous variants: 258 observed, 217.02 expected, observed/expected ratio (o/e) 1.19, 90% interval 1.07 to 1.32.
Homologues: Orthologues: chimpanzee COL26A1 (99% identical), macaque COL26A1 (96% identical), dog COL26A1 (89% identical), mouse Col26a1 (88% identical), guinea pig COL26A1 (88% identical), rat Col26a1 (86% identical), rabbit COL26A1 (68% identical), tropical clawed frog col26a1 (58% identical), pig COL26A1 (50% identical). Paralogues in human: COL11A1 (31% identical), COL5A1 (31% identical), COL11A2 (30% identical), COL1A1 (29% identical), COL4A5 (29% identical), COL4A2 (28% identical), COL2A1 (28% identical), COL1A2 (27% identical), COL4A1 (27% identical), COL5A2 (27% identical), COL4A3 (27% identical), COL4A4 (27% identical), and 25 more.
Diseases named in the same sentence as COL26A1 in open-access papers:
COL26A1 is named in the same sentence as 16 diseases in open-access papers, as found by Europe PMC text mining. Sharing a sentence is not in itself a finding about the gene and the disease. The quoted sentences say what the papers report.
asthma (4 papers, 2012 to 2024). "COL26A1 has yet to be functionally characterized, with a possible role in aspirin-intolerant asthma." (PMID 25887117, 2015).
small cell lung carcinoma (1 paper, 2024). Small cell lung cancer (SCLC) is a highly aggressive malignant neoplasm, accounting for 10-15% of lung cancer cases, characterized byrapid growth, and early metastasis. "The expression of COL26A1 has been observed to be downregulated in patients with transformed small-cell lung carcinoma who respond well to PD-L1 inhibitors." (PMID 38797520, 2024).
COL26A1 also shares sentences with these, for which no sentence is quoted: tumor (5 papers); cancer (2); bipolar disorder (1); chordoma (1); diabetes (1); endometritis (1); Hypertension (1); lung adenocarcinoma (1); lung carcinoma (1); nasal polyps (1); neuroblastoma (1); pancreatic cancers (1); polyp (1); respiratory disease (1).